SFTPC (surfactant protein C)
Description:
Pulmonary surfactant associated proteins promote alveolar stability by lowering the surface tension at the air-liquid interface in the peripheral air spaces.
Synonyms: SP-C; SFTP2; PSP-C; SMDP2; BRICD6
Tractability: Antibody: its Gene Ontology location is reachable by antibodies, with high confidence; UniProt places it where antibodies can reach, with medium confidence. PROTAC: ubiquitination databases record sites on it.
Gene: Protein-coding gene on chromosome 8 (22,156,913 to 22,164,479, forward strand). Ensembl gene ENSG00000168484.
Subcellular location: Secreted, extracellular space, surface film
Pathways (Reactome):
Disease: Defective CSF2RA causes SMDP4; Defective CSF2RB causes SMDP5; Defective pro-SFTPC causes SMDP2 and RDS
Metabolism of proteins: Surfactant metabolism
Gene Ontology:
Molecular function: identical protein binding; protein binding
Biological process: respiratory gaseous exchange by respiratory system
Cellular component: alveolar lamellar body; clathrin-coated endocytic vesicle; endoplasmic reticulum membrane; extracellular region; lamellar body; multivesicular body lumen
Genetic constraint (gnomAD): Loss-of-function variants: 12 observed, 19.44 expected, observed/expected ratio (o/e) 0.62, 90% interval 0.4 to 1. The upper end of that interval is the gene's LOEUF score, 1, which puts it in group 4 of 6, group 1 being the genes least tolerant of losing a copy. Missense variants: 219 observed, 266.83 expected, observed/expected ratio (o/e) 0.82, 90% interval 0.73 to 0.92. Synonymous variants: 123 observed, 110.5 expected, observed/expected ratio (o/e) 1.11, 90% interval 0.96 to 1.29.
Homologues: Orthologues: chimpanzee SFTPC (99% identical), macaque SFTPC (93% identical), rat Sftpc (83% identical), mouse Sftpc (82% identical), dog SFTPC (82% identical), guinea pig SFTPC (79% identical), pig SFTPC (69% identical), tropical clawed frog sftpc (40% identical).
Diseases named in the same sentence as SFTPC in open-access papers:
SFTPC is named in the same sentence as 71 diseases in open-access papers, as found by Europe PMC text mining. Sharing a sentence is not in itself a finding about the gene and the disease. The quoted sentences say what the papers report.
pulmonary fibrosis (50 papers, 2011 to 2026). Chronic progressive interstitial lung disorder characterized by the replacement of the lung tissue by connective tissue, leading to progressive dyspnea, respiratory failure, or right heart failure. "Recent study suggests that dysregulated cholesterol metabolism mediates abnormal alveolar remodeling and drives pulmonary fibrosis, with surfactant protein C deficiency exacerbating this process by disrupting cholesterol homeostasis." (PMID 40642530, 2025). "Mutations on surfactant protein C (SFTPC), particularly I73T, are associated with a toxic gain of function that causes misfolding and the accumulation of immature SFTPC proteins, triggering pulmonary fibrosis (PF)." (PMID 40225577, 2025). "Previous research has found that mutations in the SFTPC gene are associated with several familial and sporadic interstitial lung diseases, including pulmonary fibrosis." (PMID 38575860, 2024). "A mutated surfactant protein C gene (SftpcL184Q, Gene ID: 6440) in newborns has been associated with respiratory distress syndrome and pulmonary fibrosis." (PMID 39201410, 2024). "Combined with in vitro experimental validation of the SFTPC gene, these results indicate the contribution of lung fibrosis genes to the capacity of marine mammals to reduce the risk of DCS during diving." (PMID 38575860, 2024). "As a result, de novo mutations in the SFTPC gene are considered rare contributors to the pathogenesis of sporadic pulmonary fibrosis." (PMID 39768847, 2024). "As an example of the patient-derived iPSC-derived AEC harboring SFTPC mutations that cause pulmonary fibrosis, the I73T mutation has recently been reported, in which aberrant SFTPC trafficking, impaired autophagy, and metabolic reprogramming were observed." (PMID 37701577, 2023). "Some monogenic forms of pulmonary fibrosis are associated with expression of mutant surfactant protein C (SFTPC)." (PMID 34049951, 2022). "Among surfactant proteins variants of surfactant protein C (SP-C), surfactant protein A2 (SP-A2) and surfactant protein A1 (SP-A1) have been associated to familiar pulmonary fibrosis, while they are rare in sporadic IPF." (PMID 34200784, 2021). "SFTPC mutations act in an autosomal dominant fashion and more commonly presents with chILD or idiopathic pulmonary fibrosis than neonatal RDS." (PMID 35098209, 2021). "Guided by clinical evidence, we have developed a mutant model of pulmonary fibrosis leveraging the PF-linked missense isoleucine to threonine substitution at position 73 [I73T] in the alveolar type-2 cell-restricted Surfactant Protein-C [SP-C] gene [SFTPC]." (PMID 33968067, 2021). "While the majority of studies linked SFTPC mutations to the familial form of pulmonary fibrosis, genetic mutations in SFTPC were also detected in a subset of patients suffering from sporadic IPF." (PMID 32431623, 2020). "Genomic analysis has revealed several genetic variants correlated with lung fibrosis, such as surfactant protein C (SPC), MUC5B, telomerase reverse transcriptase (TERT), telomerase RNA component (TERC) and regulator of telomere elongation helicase 1 (RTEL1)." (PMID 33117807, 2020). "As an example of such genetic predispositions related to pulmonary fibrosis, mutations in SFTPC, a gene encoding surfactant protein C (pro-SPC, a representative marker of type II AECs), have been associated with familial pulmonary fibrosis (FPF) kindreds." (PMID 27899769, 2016). "Recent studies demonstrated a strong association between surfactant protein C gene mutations and familial idiopathic pulmonary fibrosis." (PMID 21660239, 2011). "Subsequently, we conducted a thorough investigation to determine whether lung fibrosis resulting from SFTPC gene mutations influences cellular proliferation and apoptosis during the ER stress phase." (PMID 38575860, 2024). "The previous studies demonstrated that mutations or deletions in SFTPC could cause idiopathic pulmonary fibrosis (IPF)." (PMID 39346732, 2024).
pulmonary fibrosis (continued). "Mutations or deletions in SFTPC cause idiopathic pulmonary fibrosis (IPF)." (PMID 39346732, 2024). "SFTPC mutations may promote lung fibrosis by inducing endoplasmic reticulum stress and apoptotic cell death in AEC II." (PMID 35935869, 2022). "SFTPC-associated familial forms of pulmonary fibrosis are characterized by reduced penetrance suggesting that further endogenous or exogenous elements might back the marked variety of pulmonary fibrosis predisposed by SFTPC mutations." (PMID 35939165, 2022). "Even though these early studies suggested an inherited risk, the first specific disease associated gene variants were identified after 2000 and included surfactant protein mutations among familial cases of pulmonary fibrosis, specifically in the genes for surfactant protein C (SFTPC) and SFTPCA." (PMID 26400796, 2015). "Indeed, we now recognize that a subset of surfactant protein C mutations, which causes a familial form of pulmonary fibrosis, acts through mistrafficking of surfactant protein C, accumulation within endosomes, and a late block of macroautophagy and mitophagy within type II alveolar epithelial cells." (PMID 29459894, 2018). "Our in vivo data also indicated that delivery of an adenovirus-mediated Yy1 shRNA vector under the control of the surfactant protein C promoter protected mice from PS-NPs-induced pulmonary fibrosis." (PMID 41560817, 2026). "Pathogenic mutations causing pulmonary fibrosis have been identified in two different groups of genes, surfactant related genes (SRG) such as SFTPC and SFTPA2, or telomere related genes (TRG) such as TERT and RTEL1." (PMID 38069069, 2023). "Mutations in genes predominantly expressed in AT2 cells, such as surfactant protein C (SFTPC), surfactant protein A2, and ABCA3, have been associated with human lung fibrosis, including IPF13." (PMID 37653024, 2023). "The results showed that in AT-II-associated proteins (LAMP3, ABCA3, and SFTPC), the expression of ABCA3 and SFTPC was significantly downregulated, which can also suggest the loss of AT II in pulmonary fibrosis." (PMID 34645797, 2021). "HDAC inhibitors attenuate BLM-induced pulmonary fibrosis by restoring surfactant protein C expression in alveolar epithelial type II cells." (PMID 33803282, 2021). "There are many candidate genes implicated in pulmonary fibrosis, such as IGF-I, IGFBPs, ELMOD2, TERT, TERC, SFTPC, SFTPA2), and MUC5B." (PMID 26447616, 2015). "As MUC5B, SFTPC, and SFTPA1 are expressed by alveolar type II cells, this raises the possibility that injury of these cells is a critical pathogenic mechanism in pulmonary fibrosis." (PMID 24391588, 2013). "The implication of genetic polymorphisms in SFTPA2, SFTPC, MUC5B as well as DSP (encoding desmoplakin) as risk factors for pulmonary fibrosis suggest that the integrity of the barrier function is critically important in maintaining lung homeostasis." (PMID 24391588, 2013). "Therefore, we investigated the function of the USP11-mediated SFTPC protein abundance during lung fibrosis." (PMID 40225577, 2025). "Double-staining showed that the expression of the ER stress marker CHOP and NLRP3 colocalized with surfactant protein C (SPC) in the BLM model group, indicating that ER stress and NLRP3 inflammasome activation were closely linked in type II AECs in BLM-induced pulmonary fibrosis." (PMID 36033388, 2022). "Pathogenic SFTPC variants located in the C-terminal BRICHOS domain, which acts as a chaperone to promote protein stability, result in increased endoplasmic reticulum stress, inflammation, and spontaneous pulmonary fibrosis in a murine model." (PMID 35098209, 2021). "In human IPF lung tissue, we found that MUC5B is co-expressed with surfactant protein C in columnar epithelial cells lining honeycomb cysts and in type 2 alveolar epithelia, indicating that cell types involved in lung fibrosis in the distal airspace also express MUC5B." (PMID 30560893, 2018).
pulmonary fibrosis (continued). "Three studies evaluated biomarkers for lung fibrosis (vimentin,α-SMA, surfactant protein-C, MCP-1, and Krebs von den lungen-6& KC) resulting from inflammation, and three studies evaluated biomarkers relatedto oxidative stress (ROS, SOD, GSH-PX, and CAT)." (PMID 39692326, 2024). "This study also supports the previous finding that high levels of NFkB, TNF, SFTPC, MUC5B, and other proteins could promote lung fibrosis." (PMID 33362771, 2020).
interstitial lung disease (35 papers, 2005 to 2025). A diverse group of lung diseases that affect the lung parenchyma. "Interstitial lung disease associated with mutations in the surfactant protein C gene (SFTPC) is a rare condition." (PMID 40575365, 2025). "This case series aimed to investigate surfactant protein C deficiency as a potential diagnosis in young adults with CT findings suggestive of interstitial lung disease and to recommend genetic testing." (PMID 40575365, 2025). "In doing so we were able to define key differences in trafficking and post-translational processing between WT SP-C and a well described interstitial lung disease-associated SFTPC mutant, SP-CI73T." (PMID 41256658, 2025). "A number of risk factors have been found to contribute to the pathogenesis of IPF, including genetic predisposition; for example, mutations in the surfactant protein C (SFTPC) gene have implications for the familial forms of interstitial lung disease." (PMID 40497957, 2025). "Treatment for interstitial lung disease (ILD) related to SFTPC mutations includes corticosteroids, hydroxychloroquine, and other medications." (PMID 40575365, 2025). "Several studies have linked mutations in SFTPC within the BRICHOS domain of the proprotein (proSP-C) to interstitial lung diseases." (PMID 38575860, 2024). "Mutations in SFTPA1, SFTPA2, SFTPB, and SFTPC—excluding SFTPD—are recognized as monogenic causes of interstitial lung disease." (PMID 39768847, 2024). "The abnormality of surfactant protein C (SFTPC) has been linked to the development of a number of interstitial lung diseases, according to mounting evidence." (PMID 37955668, 2023). "The first genetic association between the surfactant and IPF was obtained when Nogee and colleagues reported a coding mutation in SFTPC gene in an infant and her mother, both affected with interstitial lung disease (ILD)." (PMID 37181377, 2023). "Interstitial Lung Disease (ILD)-associated mutations in surfactant protein C (SP-C) render the protein prone to aggregation." (PMID 35383173, 2022). "Mutations in the gene SFTPC, encoding surfactant protein C (SP-C), are associated with interstitial lung disease in children and adults." (PMID 34138759, 2021). "The identification of SFTPC mutations has led to significant advances in the diagnosis of interstitial lung disease in infancy and childhood." (PMID 31462320, 2019). "Monoallelic mutations of the Surfactant Protein C gene (SFTPC) are associated with Interstitial Lung Disease in children." (PMID 26925580, 2016). "This study details the utilisation of hospital services and associated costs in a single case of surfactant protein C deficiency, an example of childhood interstitial lung disease." (PMID 24642012, 2014). "On the 129S6 background Sftpc -/- mice develop parenchymal lung injury with age that is similar to the interstitial lung disease (ILD) reported for individuals with deficiencies of SP-C or SFTPC mutations." (PMID 23399055, 2013). "Mutations in the surfactant protein C (SFTPC) gene have been mostly associated with interstitial lung disease." (PMID 22448331, 2012). "There is growing evidence that mutations in the surfactant protein C gene play a role in the pathogenesis of certain forms of pediatric interstitial lung disease." (PMID 15819986, 2005). "We present 2 cases of young adults with SFTPC mutations related to interstitial lung disease (ILD)." (PMID 40575365, 2025). "CC10 and SFTPC are not only markers of unique cell families in terminal bronchioles and alveoli but are also associated with a variety of pulmonary disorders ranging from interstitial lung diseases to cancer and environmental exposures." (PMID 34911549, 2021). "Bi-allelic ABCA3 mutations and mono-allelic mutations of SFTPC, the gene encoding surfactant protein-C (SP-C), may also cause later-onset, progressive interstitial lung disease spanning from infancy to adulthood." (PMID 21867529, 2011).
interstitial lung disease (continued). "In line with this, surfactant protein-A and surfactant protein-D may be involved in smoking-related lung diseases, and cystic changes and paraseptal emphysema have been previously reported in interstitial lung disease associated with mutations in the surfactant protein-C gene." (PMID 22866751, 2012). "Heterozygous mutations of SFTPC, the gene encoding surfactant protein C (SP-C), cause sporadic and familial interstitial lung disease (ILD) in children and adults." (PMID 21092132, 2010). "AT2 dysfunction underlies many lung diseases, including interstitial lung disease (ILD), in which some inherited forms result from the mislocalization of surfactant protein C (SFTPC) variants." (PMID 39815007, 2025). "The most common mutation in surfactant protein C gene (SFTPC), SFTPCI73T, causes interstitial lung disease with few therapeutic options." (PMID 39405113, 2024). "Mutations in the surfactant protein C gene (SFTPC) result in interstitial lung disease (ILD)." (PMID 31462320, 2019). "In interstitial lung diseases caused by SFTPC mutations, mutant surfactant protein C has been shown to accumulate in the endoplasmic reticulum (ER), leading to ER stress, type II AEC injury, inflammation and the activation of apoptosis." (PMID 24927752, 2014). "The results of a recent randomized controlled phase 2 trial of HCQ in 35 patients with various forms of interstitial lung disease (caused by the pathogenic variants of SFTPC, ABCA3, NKX2.1, TBX4, COPA, etc.)did not identify an overall HCQ treatment effect." (PMID 41181172, 2025). "Understanding the pathobiology underlying IPF initiation and progression has been facilitated by the characterization of high effect size variants in the surfactant protein C (SFTPC) gene found in patients with familial pulmonary fibrosis, sporadic IPF, and childhood interstitial lung disease." (PMID 40591409, 2025). "Furthermore, pathogenic variants of SFTPC and some of the ABCA3 genes are recessive and dominantly inherited and have been linked to chronic interstitial lung disease (ILD) in term newborns, children, and adults." (PMID 38203821, 2024). "Heterozygous SFTPC mutations concomitant, as well as heterozygous mutations in ATP-binding cassette transporter A3 (ABCA3) in infants with interstitial lung diseases (ILD), might likely led to development of clinical ILD." (PMID 35939165, 2022).
lung carcinoma (19 papers, 2010 to 2025). "The pathogenesis of lung cancer induced by EML4-ALK has been confirmed by evidence, and the rapid development of lung cancer is mainly caused by overexpression of EML4-ALK in type II alveolar epithelial cells through the Clara cell secretory protein (CCSP) or surfactant protein c (SPC) promoter." (PMID 36591504, 2022). "In detail, variants in the SFTPA2 gene (the surfactant protein A) are associated with ER stress and an increased risk of developing lung cancer in smokers; those in the SFTPC gene (the surfactant protein C) lead to a misfolded SP-C, which thus accumulates in the ER, causing ER stress." (PMID 36553114, 2022). "The top 10 most significant DEGs, including upregulated MAGE family genes, which are highly specific to lung cancer, and downregulated SFTPC, crucial for maintaining normal lung function, were visualized as a heatmap." (PMID 41223031, 2025). "In this study, we first systematically analyzed the expression of eight AT II-associated genes (AQP4, SFTPB, SFTPC, SFTPD, CLDN18, FOXA2, NKX2-1, and PGC) in lung cancer." (PMID 36203529, 2022). "In this study, we comprehensively analyzed the gene expression, prognosis value, genetic alteration, and immune cell infiltration of eight AT II-associated genes (AQP4, SFTPB, SFTPC, SFTPD, CLDN18, FOXA2, NKX2-1, and PGC) in Nonsmall Cell Lung Cancer (NSCLC)." (PMID 36203529, 2022). "Furthermore, this potent derivative was also evaluated in vivo in a transgenic mouse lung cancer model expressing a mutated and constitutively active c-RAF kinase (c-RAF-1-BxB) under the control of the human surfactant protein C (SP-C) promoter in type II alveolar pneumocytes." (PMID 25674792, 2015). "After entering the bloodstream, the exosomes rely on integrinβ4 on their surface to bind specifically to surfactant protein C (SPC) on A549 cells, achieving lung cancer-specific targeting." (PMID 40869279, 2025). "Especially, five lung cancer-related genes including CYP4B1, CHRDL1, SFTPC, SFTPB, and AGER were consistently downregulated in both LUAD and LUSC had a positive correlation with TMPRSS2, exhibited an opposite effect on the prognosis of LUAD and LUSC." (PMID 35082790, 2021). "In addition to genes associated with smoking the AC1/AC2 classifier included several genes implicated in lung cancer tumorigenesis, such as KITID1MMP7MYCNXRN2, and CYP24A1, as well as type II pneumocyte marker genes such as NKX2-1 (TTF1/TITF1), LAMP3 (CD208), and surfactant proteins SFTPB and SFTPC." (PMID 22676229, 2012). "The best three single gene discriminators are CAV1, SFTPC and VWF for lung cancer, having the same classification accuracy, 99.1% on the training set and 98.2% and 100%, 96.3% and 82.5%, and 88.9% and 100% on the two test sets, respectively." (PMID 21060876, 2010). "Studies have determined that SFTPC is overexpressed in long-term surviving NSCLC patients, indicating its potential as a biomarker for lung cancer treatment.Furthermore, activation of the BTLA/HVEM pathway is regarded as the initiator of immune escape in lung cancer." (PMID 37187731, 2023).